PSMB4 (proteasome 20S subunit beta 4)
Diseases named in the same sentence as PSMB4 in open-access papers:
PSMB4 is named in the same sentence as 42 diseases in open-access papers, as found by Europe PMC text mining. Sharing a sentence is not in itself a finding about the gene and the disease. The quoted sentences say what the papers report.
ovarian carcinoma (7 papers, 2017 to 2024). A malignant neoplasm originating from the surface ovarian epithelium. "Notably, PSMB4 (proteasome subunit beta type-4), a protein of the ubiquitin-proteasome degradation pathway, has been identified as the first proteasomal subunit with oncogenic properties and associated to poor prognosis in several tumors including melanoma, breast, and ovarian cancers." (PMID 39693144, 2024). "An increased level of PSMB4 has been observed in several solid cancers such as breast cancer, ovarian cancer, multiple myeloma, pulmonary neuroendocrine tumors and glioblastoma 58-63." (PMID 35693739, 2022). "Overexpression of PSMB4 increases cellular growth and the viability of breast cancer and ovarian cancer, leading to a poor prognosis." (PMID 32489334, 2020). "In ovarian cancer, high expression of PSMB4 was closely related to tumor grade, tumor stage, lymph node, ascites and Ki-67, as well as worse OS." (PMID 27966459, 2017). "For instance, PSMB4, a subunit of the 20S core complex, has been shown to be upregulated in epithelial ovarian cancer, and overexpression of PSMB4 was significantly related to clinicopathological characteristics and worse prognosis in epithelial ovarian cancer patients." (PMID 27966459, 2017). "Intriguingly, amplification of PSMB3, PSMB4, and PSMD4 have also been observed in breast- and ovarian cancer." (PMID 36123629, 2022).
breast carcinoma (6 papers, 2016 to 2024). "Conversely, high expression of proteasome subunits PSMB7 and PSMB4 has been shown to be associated with decreased breast cancer patient survival and poor prognosis, respectively." (PMID 26930717, 2016). "Overexpression of PSMB4 promotes the proliferation and survival of breast cancer cells, lleading to an unfavorable prognosis." (PMID 38418940, 2024). "A recent study revealed that PSMB4 overexpression in breast cancer cell lines and tissues enhanced the cell growth and viability and resulted in a poor prognosis." (PMID 35693739, 2022).
depression (6 papers, 2012 to 2026). "Elsewhere, PSMB4, which encodes a member of the proteasome B-type family, was associated with depression risk (p = 2.36 × 10−05)." (PMID 32413284, 2020). "For example, single nucleotide polymorphisms (SNPs) in the PSMB4 and T-bet (Tbx 21) genes are strongly involved in the susceptibility to major depression." (PMID 22860054, 2012). "Among the top 10 DMP genes, we found two of them were related to mental health disorders: RIOK3 (cg21515243) was a gender-specific risk factor for Alzheimer’s disease and PSMB4 (cg01334186) involved inflammation was related to the susceptibility to major depression." (PMID 36344488, 2022). "However, we conducted a cross-analysis of potential sites associated with depression and schizophrenia, which revealed four intersecting sites: BTN3A1, CYP21A2, PSMB4, and TIMP4." (PMID 38637810, 2024). "We have identified shared comorbidity loci between schizophrenia and depression, including BTN3A1, PSMB4, and TIMP4." (PMID 38637810, 2024). "The team of Wong ML, in 2008, discovered the correlation between depression and two SNPs of rs17244587 in TBX21 and rs2296840 in PSMB4 genes in the American-Mexican population." (PMID 37950255, 2023). "Shared comorbidity loci between depression and schizophrenia included BTN3A1, PSMB4, and TIMP4." (PMID 38637810, 2024).
hepatocellular carcinoma (5 papers, 2016 to 2022). A malignant tumor that arises from hepatocytes. "Upregulation of PSMA6, PSMB4, PSMC2 and PSMD12 was also observed in hepatocellular carcinomas in p21-HBx transgenic mice." (PMID 27966459, 2017). "Aberrant expression of members of the proteasome subunit beta (PSMB) family (including PSMB2, PSMB4, PSMB7 and PSMB8) has been reported in hepatocellular carcinoma (HCC)." (PMID 36062301, 2022).
melanoma (4 papers, 2020 to 2024). A malignant, usually aggressive tumor composed of atypical, neoplastic melanocytes. "For the level of mRNA expression in the TCGA database and melanoma cell lines, SLC39A14, PSMB4, CRELD2, CDKN2A and TIMP1 were higher in SKCM tissues than in normal skin tissues, and NDRG1, ATF3, and JUND had an opposite trend." (PMID 36226170, 2022).
liver cancer (3 papers, 2011 to 2023). An epithelial or non-epithelial malignant neoplasm that arises from the liver.
Bladder Cancer (2 papers, 2020 to 2024). "Our findings suggest the role of PSMB4 as a potential target for therapeutic strategies against human bladder cancer." (PMID 38791597, 2024). "This study aimed to explore the effect of PSMB4 knockdown on the survival, migration, and angiogenesis of human bladder cancer cells with different degrees of malignancy." (PMID 38791597, 2024). "To clarify the role of PSMB4 in vivo, we established a bladder cancer metastasis model in nude mice by intravenous injection to evaluate the effect of PSMB4 knockdown on metastasis." (PMID 38791597, 2024). "Inhibition of PSMB4 resulted in a decrease in the migration ability of human bladder cancer cells through a reduction in the expression of the adhesion-related proteins FAK and MLC." (PMID 38791597, 2024). "We analyzed the effects of PSMB4 knockdown in bladder cancer cells and endothelial cells in the tumor microenvironment." (PMID 38791597, 2024). "Analysis of a bladder carcinoma tissue array showed that the expression of PSMB4 was higher in tissues from patients with low- and high-grade urothelial carcinoma than in nonneoplastic bladder tissues." (PMID 38791597, 2024). "Although silencing PSMB4 reduced the migration ability of human bladder cancer cells, different signals may be involved in low- and high-grade bladder cancers." (PMID 38791597, 2024). "In the future, obtaining bladder cancer cells derived from patients to confirm the inhibitory effects of PSMB4 on growth, migration, and angiogenesis will provide further evidence supporting the role of PSMB4 in bladder cancer." (PMID 38791597, 2024). "PSMB4 inhibition reduces HUVEC tube formation, possibly due to the decreased secretion of VEGF from bladder cancer cells." (PMID 38791597, 2024). "However, the role of PSMB4 in bladder cancer remains unclear." (PMID 38791597, 2024). "In our results, the decrease in VEGF-B, but not VEGF-A, -C, and -D, in PSMB4-knockdown bladder cancer cells was verified." (PMID 38791597, 2024). "Knockdown of PSMB4 decreased VEGF-B secretion and angiogenesis in human bladder cancer." (PMID 38791597, 2024). "Furthermore, the suppression of PSMB4 decreased the levels of vascular endothelial factor B (VEGF-B), resulting in lower angiogenic abilities in human bladder cancer cells." (PMID 38791597, 2024). "Moreover, knockdown of PSMB4 inhibited HUVEC tube formation, possibly due to the reduction in the VEGF-B content in the conditioned medium collected from bladder cancer cells." (PMID 38791597, 2024). "Although primary cells from patients were not used, a bladder cancer tissue array was used for HE and IHC staining to show that the expression of PSMB4 was higher in cancer tissues than in adjacent normal tissues." (PMID 38791597, 2024).
glioblastoma (2 papers, 2022 to 2024). The most malignant astrocytic tumor (WHO grade IV). "In our previous study, the levels of adhesion-associated proteins, including p-FAK, p-paxillin, integrin β1, and integrin β3, were reduced after knockdown of PSMB4 expression in LN229 human glioblastoma cells." (PMID 38791597, 2024).
lung adenocarcinoma (2 papers, 2020 to 2021). A carcinoma that arises from the lung and is characterized by the presence of malignant glandular epithelial cells. "Seven other 26S/20S proteasome subunits were isolated (q < 0.05; PSMD12, PSMB4, PSMA6, PSMB6, PSMC1, PSMD3, and PSMB3), illuminating the importance of the 26/20S proteasome integrity in lung adenocarcinoma genome maintenance." (PMID 34070461, 2021).
metastatic disease (2 papers, 2024). "In particular, PSMB4, RUVBL2, and ANKAR EV protein levels were increased in patients with metastatic disease, whereas RAP2B, SERPINA12, and IGLV4-69 abundance levels were decreased in the cEVs of patients with metastasis." (PMID 39693144, 2024). "In particular, PSMB4, RUVBL2 and ANKAR EV protein levels were increased, whereas RAP2B, SERPINA12 and IGLV4-69 abundance levels were decreased in the cEVs of patients with metastatic disease." (PMID 36993200, 2024).
COVID-19 (1 paper, 2022). A disease caused by infection with severe acute respiratory syndrome coronavirus 2. "Moreover, PSMB1, PSMB4, PSMB8 were not overexpressed in COVID-19 patients PBMCs." (PMID 35327634, 2022).
diabetes (1 paper, 2020). "In the group enriched with diabetic patients (6 out of 9 patients), seven proteasome genes (PSME4, PSMA7, PSMB4, PSMB6, PSMC4, PSMD7 and PSMD8) and three genes previously associated with common diabetes (SNX17, PARK7/DJ-1 and ATP5B) were highly expressed." (PMID 32302349, 2020).
ependymoma (1 paper, 2008). A WHO grade II, slow growing tumor of children and young adults, usually located intraventricularly. "Once the tags were ranked based on the difference in tag count between the recurrent sample of pair R1 and the primary, CHI3L1, S100A10 and PSMB4 were revealed as the top three genes upregulated as a consequence of the gain of 1q in recurrent ependymoma." (PMID 18781180, 2008).
gastric cancer (1 paper, 2022). A primary or metastatic malignant neoplasm involving the stomach. "Recently, high expression of several of these PSM genes (e.g. PSMA1, PSMB4, and PSMD2) has been correlated with poor prognosis in a number of cancer types, including breast-, lung-, and gastric cancer." (PMID 36123629, 2022).
triple-negative breast carcinoma (1 paper, 2020). An invasive breast carcinoma which is negative for expression of estrogen receptor (ER), progesterone receptor (PR), and human epidermal growth factor receptor 2 (HER2). "Moreover, in triple-negative breast cancer cells, the expression of proteasomal genes PSMB4 and PSMB5 was dependent on the expression of splice factors PRPF8 and PRPF38A." (PMID 32545483, 2020).
urothelial carcinoma (1 paper, 2024). A malignant neoplasm derived from the transitional epithelium of the urinary tract (urinary bladder, ureter, urethra, or renal pelvis). "PSMB4 was highly expressed in patients with low- and high-grade urothelial carcinoma." (PMID 38791597, 2024).
viral infections (1 paper, 2022). "Taken together, PSMB4 may be involved in the cellular defense mechanism against viral infections." (PMID 36298834, 2022).
tumor (17 papers, 2015 to 2025). "The underlying relationship between tumor promoting and aging accelerating effects of PSMB4 calls for further exploration." (PMID 38572516, 2024). "PSMB4 facilitates cancer cell survival and tumor growth and is associated with poor prognosis in various tumor types, such as breast, lung, skin, and ovary." (PMID 38572516, 2024). "In this study, overexpression of PSMB4 mRNA and higher levels of proteins encoded by PSMB4 were found in ccRCC tissues compared to normal tissues, and was significantly related with patients' individual cancer stages and tumor grades." (PMID 35693739, 2022). "MHC class I restricted IFN-γ+ CD8 T cells specific for Phage encoded TMP-1 of E. hirae cross reacts with tumor specific PSMB4 to provide antitumor immunity." (PMID 33708214, 2021). "CD8 + T cells that are cross-reactive with this epitope demonstrated robust activity against a protein encoded by the proto-oncogene PSMB4, which markedly improved ICB-mediated tumor control in both mice and humans." (PMID 40264971, 2025). "We observed higher expression of PSMB1, PSMB3, and PSMB4 in tumour samples when compared to other subunits." (PMID 40862469, 2025). "HSPD1 and PSMB4 were observed to show strongly interrelated with neoplasm disease (80%) while GEMIN6 is highly interrelated with nervous system diseases (80%)." (PMID 34918006, 2022). "We observed higher expression of PSMD4 and PSMB4 protein levels in the recurrent tumors compared with the primary tumor and normal brain tissues." (PMID 32235770, 2020). "PSMB4 was identified as the first proteasomal subunit with oncogenic properties, promoting cancer cell survival and tumor growth in vivo." (PMID 25936657, 2015). "All these results showed that PSMB4 participated in the tumor development of ccRCC and could be identified as promising prognostic targets of RCC." (PMID 35693739, 2022). "The TMP1 peptide derived from enterococci (a type of intestinal bacteria) shares a strong homology with a peptide of proteasome subunit beta type-4 (PSMB4, a tumor antigen), and this homology arouses the bacteria-dependent antitumor activity of CD8+ T cells in an HLA-restricted manner." (PMID 40148310, 2025). "In the rS-pS group, some interesting genes with deviating correlation between early and late stages including PSMB4 (proteasome subunit beta type-4) with high correlation in the late stage and EEF1B2 (elongation factor 1-beta) with high correlation in the early stage of tumor tissue were identified." (PMID 33384992, 2020).
cancer (13 papers, 2011 to 2025). A tumor composed of atypical neoplastic, often pleomorphic cells that invade other tissues. "Elevated expression of PSMB4 is associated with poor prognosis in human cancer." (PMID 25936657, 2015). "Because PSMB4 was among the most effectively degraded orphan subunits and was among the most efficiently degraded endogenous proteins in a cancer cell model, we focused on this for further characterization." (PMID 39879985, 2025). "Studies have shown that PSMB4 is highly expressed in a variety of cancer types, such as breast cancer, brain glioma, ovarian cancer, and myeloma." (PMID 38791597, 2024). "Proteasome subunit type 4 (PSMB4) is highly expressed and has been identified as having oncogenic properties in a variety of cancer types." (PMID 38791597, 2024). "Proteasome subunit beta type-4, PSMB4, was identified to be putatively crucial in P. micra-associated CRC tumorigenesis and commonly overexpressed in other human cancer." (PMID 37218575, 2023). "Staining of PSMB4/6 proteins was observed as medium in both normal tissues and cancer tissues." (PMID 35693739, 2022). "Among the 224 differently regulated proteins that are more abundant in male D sites are tricarboxylate transport protein (SLC25A1), proteasome β-4 subunit (PSMB4), and type II cytoskeletal 2 oral keratin (KRT76), all with known roles in cancer (expression profiles)." (PMID 35566209, 2022). "Furthermore, co-amplification of PSM genes located in close proximity to one another (e.g. PSMB5 and PSMB11, 14q11.2; PSMB4 and PSMD4, 1q21.3; PSMB8 and PSMB9, 6p21.32) or known cancer drivers (e.g. co-amplification of ERBB2 and PSMB3) were also frequently amplified together." (PMID 36123629, 2022). "In conclusion, the comprehensive pan-cancer analysis presented here demonstrated that several PSM genes (e.g. PSMA1, PSMB4-5, PSMB8-10, PSMD2, PSMD4, PSMD11, PSME1-3, and PSMG3) may be putative biomarkers for determining prognosis and choice of treatment for different cancer types." (PMID 36123629, 2022).
infection (3 papers, 2017 to 2022). The state of being infected such as from the introduction of a foreign agent such as serum, vaccine, antigenic substance or organism. "PSMB4 affects IAV replication more significantly with MOI 0.01 than with MOI 3 in either knockdown or overexpression conditions, suggesting that more NS1 proteins from infections with a higher MOI counteract the PSMB4 protein." (PMID 36298834, 2022). "We then silenced each of the top four upregulated PSMBs (PSMB1, PSMB4, PSMB8 and PSMB9, fold change >1.5) using shRNA in HEK293T cells and examined the viral replication in PSMB-silenced cells after VSV-expressing GFP (VSV-GFP) infection." (PMID 30682859, 2019).
psychiatric disorder (1 paper, 2024). A disorder characterized by behavioral and/or psychological abnormalities, often accompanied by physical symptoms. "Therefore, targeting PSMB4 for treatment and thereby improving ubiquitin–proteasome function could be a promising approach to correct psychiatric disorders." (PMID 38637810, 2024).
PSMB4 also shares sentences with these, for which no sentence is quoted: cervical cancer (2 papers); nervous system diseases (2); acquired lipodystrophy (1); Alzheimer disease (1); autoimmune disease (1); Desminopathy (1); glioma (1); head and neck cancer (1); Hydrocephalus (1); kidney (1); kidney renal cancer (1); lipodystrophy (1); lung carcinoma (1); multiple lipomatosis (1); multiple myeloma (1); myelodysplastic syndrome (1); pancreatic cancer (1); pulmonary neuroendocrine tumors (1); sarcoma (1); schizophrenia (1); varicocele (1).